DKC1 (dyskerin pseudouridine synthase 1)
Diseases named in the same sentence as DKC1 in open-access papers (continued):
Sharing a sentence is not in itself a finding about the gene and the disease.
cancer (continued). "The data thus far suggest that alterations in DKC1 expression or activity are strongly associated with cancer, but the exact mechanism may depend on the cell, tissue, or DKC1 substrate." (PMID 36360287, 2022). "Moreover, studies reported that DKC1 upregulation is frequently observed in many different human cancers including in HCC, and HCC tissues show a positive association with nuclear DKC1 levels." (PMID 35071775, 2022). "The data so far show that alterations in DKC1 expression or activity are significantly associated to cancer, however the exact mechanism may be cell, tissue or DKC1 substrate dependent." (PMID 33461542, 2021). "Reduced levels of p27, a tumor suppressor, could at least, in part, explain why patients with mutations in DKC1 have an increased susceptibility to cancer." (PMID 27252909, 2016). "Point mutations in DKC1 gene cause the X-linked form of dyskeratosis congenital (DC), a disease characterized by multiple features including abnormalities of the skin, bone marrow failure and an increased predisposition to cancer." (PMID 26366868, 2015). "Certain members, including DKC1, PUS1, and PUS7, have been implicated in oncogenic processes such as cancer stemness, metabolic reprogramming, and immune regulation across various malignancies." (PMID 41496500, 2026). "For instance, DKC1 binds to ribosomal proteins and promotes their expression to promote cancer progression in CRC." (PMID 40483535, 2025). "The dysregulation of DKC1 has been mostly identified affecting various cancer cells in two opposing ways." (PMID 40483535, 2025). "DKC1 enhances ribosomal protein expression to promote cancer progression; PUS7 improves the proliferation and invasion of tumor cells." (PMID 41446042, 2025). "DKC1 has been affirmed to be a serviceable facilitator in diversiform cancers, but its function in GC maintains dimness." (PMID 38376551, 2024). "DKC1 is significantly upregulated in colorectal cancer tissues, acting as a critical regulator for cancer cell proliferation." (PMID 39006762, 2024). "By analyzing a pancancer survival map, this study demonstrated the relationship between DKC1 expression and survival in patients with various cancer types." (PMID 39103487, 2024). "Recent studies have shown that dysregulation of DKC1 expression in various human cancers alters cancer cell growth and metastasis." (PMID 39103487, 2024). "To determine the pattern of DKC1 dysregulation in cancer, we expanded the normal sample size by combining and mining resources from the TCGA and GTEx databases." (PMID 39103487, 2024). "To further investigate the clinical significance of DKC1 in cancer, we analyzed its role in cancer survival." (PMID 39103487, 2024). "Recent reports suggested that DKC1 expression is dysregulated in diversified human cancers, affecting tumor growth or metastasis." (PMID 38376551, 2024). "Impaired telomerase activity and gene expression in the absence of DKC1 activity leads to decreased proliferation and survival of cancer cells." (PMID 39006762, 2024). "Although the methylation pattern of DKC1 varied, an overall negative correlation was observed between DKC1 mRNA expression and DNA methylation, suggesting the complexity and cancer specificity of DKC1 regulation." (PMID 39103487, 2024). "Proteomics and RNA immunoprecipitation sequence analyses revealed that DKC1 binds to and stabilises the expression of mRNAs for a variety of ribosomal proteins, thereby accelerating the proliferation of cancer cells." (PMID 38572667, 2024). "AH.6809, fasudil, W.13, and X4.5dianilimophthalimide exhibited notably lower scores in most cancer types, suggesting their potential to inhibit DKC1-mediated oncogenic effects." (PMID 39103487, 2024). "Simultaneously, we discussed the fundamental mechanism of DKC1, thereby providing evidence for further understanding of the role of telomerase in cancer." (PMID 38082360, 2023).
cancer (continued). "DKC1 expression has been found to be strongly correlated with immune infiltration in various types of cancers." (PMID 38082360, 2023). "In this study, we conducted a comprehensive pan-cancer analysis of DKC1 using various databases and explored its biological functions." (PMID 38082360, 2023). "PUS7, PUS1, and DKC1 are significantly up-regulated in cancer tissue at both mRNA and protein levels." (PMID 37925171, 2023). "The analysis of 33 cancer datasets from the TCGA database revealed that DKC1 was highly expressed in 19 cancers compared to paracancerous and normal tissues." (PMID 38082360, 2023). "A likely explanation for this biological phenomenon is the increase of CML cancer cells’ demand for DKC1 due to its role in post-transcriptional modification of rRNA necessary for the maintenance of an effective process of translation." (PMID 36871092, 2023). "Dyskerin (DKC1), encoded by the DKC1 gene within Xq28, is a telomerase co-factor stabilizing telomerase RNA component (TERC) and overexpressed in various cancers." (PMID 37434223, 2023). "The results demonstrate that DKC1 expression is negatively associated with tumor-associated fibroblasts in BRCA, BRCA-basal, LUSC and STAD tumors, whereas it is positively related to cancer-associated fibroblasts in KIRP, KIRC and MESO." (PMID 38082360, 2023). "The results suggest that proper expression of DKC1 is related to the pathogenesis of cancer and can guide the diagnosis and treatment of cancer, as well as the evaluation of prognosis and survival rate." (PMID 38082360, 2023). "The phosphorylation sites of DKC1 vary depending on the type of cancer, and many of these sites are concentrated at the C-terminus of the protein." (PMID 38082360, 2023). "For NVL2, RUVBL1, and DKC1, the amplification frequency >5% occurred in eight, seven, and five cancer types, respectively." (PMID 36239411, 2023). "Dysregulation of DKC1 in certain cancer types leads to aberrant ribosome biogenesis and impaired protein synthesis, resulting in a tumor-suppressive effect by impairing cell proliferation and promoting cell cycle arrest." (PMID 37612540, 2023). "Taken together, these data confirmed that knockout of DKC1 hampered the metastatic ability of cancer cells and accelerated cell senescence." (PMID 38082360, 2023). "Next, we applied the stage plot panel under GEPIA2 tool to detect the expression level of DKC1 in different cancer stages with a box plot." (PMID 38082360, 2023). "We also investigated the correlation of DKC1 methylation level and phosphorylation level with the survival rate of cancer patients." (PMID 38082360, 2023). "DKC1 is highly expressed in a variety of cancer tissues and high DKC1 expression correlates with poor prognosis." (PMID 37628759, 2023). "Depletion of DKC1 can inhibit the abilities of cancer cells to proliferate, migrate, and invade by arresting the cell cycle and inducing cell senescence." (PMID 38082360, 2023). "Dyskerin (DKC1), encoded by the DKC1 gene on X chromosome, is a telomerase co-factor stabilizing telomerase RNA component (TERC), whereas telomerase plays key roles in cancer development and progression." (PMID 37434223, 2023). "All these findings collectively suggest that DKC1 contributes to cancer development and progression in telomerase-dependent and independent manners." (PMID 37434223, 2023). "Dyskeratosis congenita 1 (DKC1), a critical component of telomerase complex, is highly expressed in a variety of human cancers." (PMID 38082360, 2023). "Studies have shown that DKC1 can be involved in cancer progression by promoting angiogenesis and is closely related to oxidative stress." (PMID 35734237, 2022). "The function of DKC1 in the occurrence and development of cancer is more well-studied, but little is known about the function of other pseudouridase enzymes, and only a handful of studies have shown their activity or expression related to tumors." (PMID 36360287, 2022).
cancer (continued). "Patients with ECs harboring a mutant DKC1 gene seemed to have a better clinical outcome, compared with cancers carrying a wild-type DKC1 gene." (PMID 33450922, 2021). "Expression of DKC1 is controlled by c-MYC transcriptionally in MYC-dependent cancers and enhances cell proliferation and growth." (PMID 33599797, 2021). "Regarding the design of drugs or screening for small molecules that inhibit PUSs activity, while several studies have attempted to generate or find compounds to diminish DKC1 activity as potential anti-cancer treatments, very little progress has followed." (PMID 33461542, 2021). "Mutations in several genes encoding protein components of H/ACA box snoRNPs, such as DKC1 and NOP10, have been identified in cancer and congenital bone marrow failure syndromes." (PMID 33288886, 2021). "In a study of HCC, it was found that DKC1 was significantly upregulated in human cancer tissue and was significantly positively correlated with the cancer cell proliferation potential, advanced clinical stage and prognosis of HCC patients." (PMID 34778277, 2021). "The observation that rRNA pseudouridylation is defective in the DKC1 hypomorphic mutant model supports the hypothesis that the intrinsic alteration of ribosome function is indeed involved in determining translational alterations and, in turn, the cancer susceptibility observed in X-DC." (PMID 29104216, 2017). "Strikingly, several studies have also confirmed that DKC1 overexpression is involved in tumorigenic processes in different types of cancer." (PMID 26366868, 2015). "In cancer cells, as in tissues, DKC1 mRNA and protein expression surpassed that in cultured normal PrECs." (PMID 19755982, 2009). "In the carcinoma tissues, DKC1 mRNA was highly significantly elevated (t-test: P<0.001) compared with benign tissues." (PMID 19755982, 2009). "Conversely, DKC1 is often highly expressed in cancers, including GBM as we described." (PMID 41510246, 2025). "In another mechanism, the DKC1 is up-regulated and plays an oncogenic role in many cancer types." (PMID 40483535, 2025). "Through one mechanism, inactivating mutations of DKC1 in dyskeratosis congenital cause the lack of pseudouridylation of rRNA, thus leading to dysfunctional translation and cancer progression." (PMID 40483535, 2025). "Notably, Pyrazofurin, when combined with trametinib (a MAP kinase inhibitor), effectively inhibits the growth of CRC cells with elevated DKC1 expression in vitro and in vivo, suggesting potential applications in DKC1‐overexpressing cancers." (PMID 39834094, 2025). "Further research indicated that DKC1 may reshape the tumor microenvironment (TME), highlighting the potential of DKC1-based cancer treatment and its usefulness in predicting the response to chemotherapy." (PMID 39103487, 2024). "We comprehensively investigated DKC1 expression levels in cancer." (PMID 39103487, 2024). "Moreover, the estimated ROC curve indicated that DKC1 mRNA expression had satisfactory sensitivity and specificity for diagnosing 16 types of cancer (AUC > 0.7)." (PMID 39103487, 2024). "Reassuringly, individuals harboring a heterozygous variant in a predominately AR gene, CTC1 or WRAP53, and including DKC1 (females), were not at increased risk of cancer." (PMID 39661387, 2024). "DKC1 has been discovered to serve as a facilitator in several cancers." (PMID 38376551, 2024). "In addition, SNORA70E binds DKC1 to regulate Ras‐associated protein 1B (RAP1B) mRNA and increase RAP1B protein level through pseudouridine modification, thereby promoting cancer cell progression in ovarian cancer." (PMID 38572667, 2024). "Furthermore, the TISCH database describes a consistent expression landscape of the gene in 72 single-cell datasets, including 31 cancer types, indicating that DKC1 is mainly expressed in malignant cells, T cells, and monocytes." (PMID 39103487, 2024).
cancer (continued). "To determine whether DKC1 down-regulation could be related to the progression of other tumoral processes, we analyzed its expression in different cancer types using The Cancer Genome Atlas database." (PMID 36732018, 2023). "Finally, we determined the effect of 10 individual factors on OS and observed that higher expression of DKC1, NVL, and GAR1 were significantly associated with nine, three, and three cancer types, respectively." (PMID 36239411, 2023). "DKC1 as one of key telomerase components is overexpressed in many types of cancer." (PMID 37434223, 2023). "Additionally, the relationship between DKC1 expression level and tumor cell proliferation has been demonstrated in various types of cancer." (PMID 38082360, 2023). "Taken together, DKC1 seemed to affect cancer cells in two opposite ways." (PMID 37612540, 2023). "DKC1 plays a complex role in cancer and exhibits both oncogenic and tumor-suppressive functions." (PMID 37612540, 2023). "Furthermore, lactate levels, produced by glucose degradation to pyruvate to generate ATP in cancer cells (the Warburg effect), were reduced up to 40% in DKC1-depleted cells, indicating that their altered metabolism relies on energy sources other than glucose." (PMID 36732018, 2023). "Through pan-cancer analysis, this study examined the expression level of DKC1." (PMID 38082360, 2023). "The findings revealed a negative correlation between DKC1 expression and cancer-associated fibroblasts in BRCA-Basal, BRCA, STAD, and LUSC using the algorithms of EPIC, TIDE, and MCPCOUNTER." (PMID 38082360, 2023). "In this context, the role of DKC1 in telomerase function may contribute to its oncogenic potential by enabling the immortalization of cancer cells and promoting cell proliferation." (PMID 37612540, 2023). "In the study, we conducted a pan-cancer analysis of DKC1 using the TCGA and GEO databases." (PMID 38082360, 2023). "The role of DKC1 in cancer prognosis could be explained by the role of DKC1 in regulating mRNA translation." (PMID 35027621, 2022). "In addition, pyrazoline and 5-fluorouracil are currently two common drugs that inhibit DKC1, opening the understanding of the role of Ψ in cancer therapy." (PMID 35484099, 2022). "Importantly, depletion of DKC1 in cells with ALT mechanism, a homologous recombination-based telomere maintenance mechanism, showed the same effect, suggesting a telomerase independent function of DKC1 for regulating cell proliferation in cancer." (PMID 33599797, 2021). "From a clinical perspective, ψ or its regulators, such as DKC1 and PUSs, may become potential biomarkers and therapeutic targets in cancer treatment." (PMID 34778277, 2021). "DKC1 was also shown to be a tumour suppressor in pituitary tumorigenesis: in this cancer type, lack of rRNA pseudouridylation causes a decrease in IRES-dependent expression of the tumour suppressor p27." (PMID 33564819, 2021). "Dyskeratosis congenita 1 (DKC1) is dysregulated in several cancers." (PMID 31857720, 2020). "The genes of the DKC1 branch including DKC1, encoding the telomerase subunit dyskerin, and the telomerase complex assembly genes Pontin (RUVBL1) and Reptin (RUVBL2) are consistently up-regulated in all cancer subtypes." (PMID 31750255, 2019). "Simultaneously, we also observed increased DKC1 expression in patients with short TL, supporting the probable involvement of this gene in progressive telomere reduction, promoting genomic instability and immortalization of cancer cells." (PMID 28666010, 2017). "In our study, a significant DKC1 overexpression associated with short TL and high telomerase levels was observed in MM compared with MGUS, confirming its participation in telomere elongation and suggesting a role for this gene in cancer development." (PMID 26366868, 2015). "Overall, DKC1 mRNA overexpression in HCC tissues was related to the cancer cell proliferation." (PMID 22912812, 2012).
cancer (continued). "We selected six DplUSE-containing genes (KIF20A, EXT2, CLDN12, MBNL2, MED18, DKC1) from the 31 orthologous genes identified by the bioinformatic script that are common to human, mouse, and zebrafish and that have a relevant physiological function in malignant neoplasms." (PMID 41505098, 2026). "DKC1-high UCEC tumors exhibited hyperproliferation, increased stemness and epithelial-mesenchymal transition, accompanied by significantly higher aneuploid, homologous recombination deficiency and micro-satellite instable scores, and higher frequencies of cancer driver aberrations." (PMID 40458122, 2025). "This study suggested that DKC1 may be a potential therapeutic target for cancer therapy." (PMID 39103487, 2024). "Therefore, DKC1 may be a valuable prognostic biomarker for the diagnosis and treatment of cancer in various tissues." (PMID 38082360, 2023). "However, the association of DKC1 with cancer occurrence and development stages is not clear, making a pan-cancer analysis crucial." (PMID 38082360, 2023). "DKC1 is among the 10% of the genes considered to be common essential genes, and complete abrogation of their expression in long-term cultures results in cell death in most normal and cancer cells (DepMap, 2022: The Cancer Dependency Map Project at Broad Institute)." (PMID 36732018, 2023). "Importantly, DKC1 silencing in lung SCC cells also resulted in the enhanced expression of proteins involved in lipid synthesis and energy generation, suggesting that modulation of DKC1 levels could rewire the metabolism in different cancer cell types." (PMID 36732018, 2023). "DKC1 overexpression may be required for telomere homeostasis in these cancer types." (PMID 33564819, 2021). "Analysis of the TCGA dataset demonstrated a more than 2-fold upregulation of DKC1 RNA levels in 69/477 (14.65%) of the endometrioid and serous ECs compared with a set of normal endometrial samples obtained from 35 EC patients, at 2–3 cm distance from the cancer margin." (PMID 33450922, 2021). "Considering that DKC1 is the direct and conserved transcriptional target of c-myc responsible for proliferative activity of cancer cells, this suggests that the role of DKC1 on cancer progression may be independent of its involvement in telomerase complex function." (PMID 26999107, 2016). "Further comparisons of cancer stemness and EMT scores showed remarkable differences, with enhanced values in DKC1-high tumors (Stemness: high vs. low, P = 3.00E-1027; EMT: P = 6.20E-105)." (PMID 40458122, 2025). "DKC1 expression is upregulated in CRC and stabilizes the mRNAs of several ribosomal proteins, thereby promoting cancer progression." (PMID 39162904, 2024). "The most notable aberrantly expressed genes were DKC1 and TRUB1, whose expression differed in 29 of the 31 cancer types." (PMID 39162904, 2024). "Regarding the clustering by rows (RBPs), there are two main clusters: the first one (mostly related to AS alterations in adult cancer), the bottom cluster in the plot, includes relevant cancer genes such as MKRN1, DKC1, or PABPC4." (PMID 39595158, 2024). "DKC1 is targeted by PARP1 and C-MYC, which exert multiple biological functions and both show enormous prognostic value in a variety of cancers." (PMID 38082360, 2023). "DKC1, RUVBL1, NHP2, and TERC expression was also inversely correlated with DNA methylation in most cancer types." (PMID 36239411, 2023). "This is supported by the DDX11, DKC1, EXOSC5, NOP56, and other genes showing differences in the most cancer types." (PMID 36698399, 2022). "We identified the top five related genes (DKC1, FAM58A, NAA10, SLC10A3, UBL4A) that mostly correlated with IRAK1 by GEPIA2.0; the heatmap displayed the correlation in pan-cancers." (PMID 35669566, 2022). "In the TCGA pan-cancer cohort, IRAK1 expression positively correlated with DKC1 (R = 0.54), FAM58A (R = 0.51), NAA10 (R = 0.54), SLC10A3 (R = 0.55), and UBLA4 (R = 0.62)." (PMID 35669566, 2022).